NRP2 (neuropilin 2)
Diseases named in the same sentence as NRP2 in open-access papers (continued):
Sharing a sentence is not in itself a finding about the gene and the disease.
cervical cancer (6 papers, 2016 to 2023). A primary or metastatic malignant neoplasm involving the cervix. "Another group has found that miRNA331-3p can suppress cervical cancer cell proliferation and E6/E7 expression by targeting Neuropilin 2 (NRP2)." (PMID 28415759, 2017). "In the future, we are going to evaluate expression of miR-331-3p and NRP2 in cervical cancer and dysplasia." (PMID 27548144, 2016). "Our future studies will examine whether miR-331-3p and its target, NRP2, are useful clinical diagnostic and/or prognostic markers for histological and cytological examination using tissue specimens and liquid-based cytology in the screening and diagnosis of cervical cancer." (PMID 27548144, 2016). "MiR-331-3p was reported to inhibit the proliferation of cervical cancer cell by targeting NRP2." (PMID 32373927, 2020). "Our study clearly suggests that the miR-331-3p and NRP2 axis may play an essential role in the growth of cervical cancer cells." (PMID 27548144, 2016). "Our findings suggest that miR-331-3p has an important role in regulating cervical cancer cell proliferation, and that miR-331-3p may contribute to keratinocyte differentiation through NRP2 suppression." (PMID 27548144, 2016). "LncRNA HOTAIR sponged miR-331-3p and elevated the expression of NRP2 in HPV positive cervical cancer, which established a negative feedback loop to govern the apoptosis of cervical cancer cells." (PMID 36438563, 2022). "In this study, we evaluated whether miR-331-3p regulates cervical cancer proliferation and the expression of the HPV-related proteins E6 and E7 by the candidate targets NRP2." (PMID 27548144, 2016). "Up-to-date, in cervical cancer, there is no report of miR-331-3p and the role of miR-331-3p and NRP2 is still unknown." (PMID 27548144, 2016). "NRP2 expression was the highest in SKG-II and significantly decreased by miR-331-3p overexpression in SKG-II, HeLa and HCS-2 cells but NACC1 was not changed by miR-331-3p overexpression in SKG-II cells (data not shown); therefore, NRP2 might act as a target of miR-331-3p in cervical cancer cells." (PMID 27548144, 2016). "In the current study, miR-331-3p overexpression significantly down-regulates NRP2, E6 and E7 proteins, and sequentially up-regulates IVL expression, which may induce keratinocytic differentiation as identified by decreased p63 protein expression in human cervical cancer cells." (PMID 27548144, 2016).
HCMV infection (6 papers, 2018 to 2026). "In both cases, Nrp2 deficiency made the cells almost completely resistant to HCMV infection." (PMID 31336680, 2019). "Thus, fibroblasts expressed similar levels of PDGFRα and Nrp2, which made fibroblasts more susceptible to HCMV infection compared to epithelial cells." (PMID 31336680, 2019). "Several molecules, such as EGFR, Integrin αvβ3, CD90, CD147, Neuropilin-2, and platelet-derived growth factor receptor alpha (PDGFRα), have been identified as receptors or co-receptors for HCMV infection in fibroblasts, epithelial, or endothelial cells." (PMID 37146061, 2023). "Small interfering RNA (siRNA)-based knockdown of Nrp2 in ARPE-19 also markedly reduced HCMV infection." (PMID 31336680, 2019). "After identifying a high-affinity interaction between Nrp2 and the pentamer, the investigators demonstrated that Nrp2 is essential for pentamer-dependent HCMV infection of endothelial and epithelial cells." (PMID 30544948, 2018). "To demonstrate whether the V160-induced mAbs inhibit HCMV infection by blocking pentamer-Nrp2 binding, we first loaded the Nrp2 ectodomain protein onto the biolayer interferometry (BLI) biosensor." (PMID 34078915, 2021). "It has recently been shown that soluble NRP2 is capable of inhibiting HCMV infection of epithelial cells, and efforts to characterize this interaction have yielded a low-resolution negative-stain electron microscopy (EM) reconstruction of NRP2-bound Pentamer." (PMID 35275718, 2022). "Ectopic expression of guinea pig cell receptors restored GPCMV infection but not human NRP2/PDGFRA, indicating a basis for the species-specific barrier for GPCMV and HCMV infection." (PMID 41805587, 2026).
lymphedema (6 papers, 2013 to 2024). Excess fluid collection in tissues, causing swelling. "Mucka P., Levonyak N., Geretti E., Zwaans B., Li X., Adini I., KlagsbrunM., Adam R., Bielenberg D. Inflammation and lymphedema areexacerbated and prolonged by neuropilin 2 deficiency." (PMID 39027126, 2024). "Although further functional and biochemical studies are needed to clarify their involvement with lymphedema and to associate NRP1 and NRP2 with lymphedema, we suggest that it is worthwhile also screening lymphedema patients for these two new candidate genes." (PMID 33212964, 2020). "Loss of neuropilin 2 in adult lymphatic endotheliumpromotes lymphedema." (PMID 39027126, 2024). "In a model of acute inflammation, NRP-2 deficiency increased vascular permeability and decreased lymphatic capillaries, resulting in severe swelling and lymphedema, and addition of Sema 3F prevented increased vascular permeability and loss of lymphatic drainage, critical to limiting inflammation." (PMID 35883654, 2022). "This study focuses on identifying rare variants in the NRP1 and NRP2 genes that could be linked to the development of lymphatic malformations in patients diagnosed with lymphedema." (PMID 33212964, 2020). "Significant frequency differences in NRP2 genotypes were revealed by comparing primary and secondary lymphedema." (PMID 39027126, 2024). "Given their functional role and our findings, we suggest that NRP1 and NRP2 should be considered candidate genes for inclusion in the gene panel for genetic testing of lymphedema patients." (PMID 33212964, 2020). "A segregation analysis in familial lymphedema cases added evidence that NRP1 and NRP2 qualify as candidate genes to include in the genetic testing of lymphedema patients." (PMID 33212964, 2020). "VEGFR3 and neuropilin-2 transcription are elevated in various lymphovenous overgrowth malformations, suggesting the underlying hyperactivation of VEGFR3 and/or its downstream signaling pathways, in contrast to primary lymphedema disorders usually characterized by attenuated VEGFR3 signaling." (PMID 38201272, 2023). "VEGF-C, neuropilin-2, and FOXC2 polymorphisms have been identified in patients with breast cancer-related lymphedema (BCRL), suggesting that baseline differences in VEGFR3 activation or lymphatic function may contribute to the risk of developing post-surgical lymphedema." (PMID 38201272, 2023). "In our study, a cohort of 235 Italian lymphedema patients, who tested negative for variants in known lymphedema-associated genes, was screened by a next-generation sequencing (NGS)-targeted panel for variants the in NRP1 and NRP2 genes." (PMID 33212964, 2020).
osteosarcoma (6 papers, 2011 to 2021). A usually aggressive malignant bone-forming mesenchymal neoplasm, predominantly affecting adolescents and young adults. "NRP2 was reported to be up-regulated in osteosarcoma cell lines and tissues, and associated with poor survival of osteosarcoma patients." (PMID 29760609, 2018). "NRP2 was overexpressed in osteosarcoma cell lines and tissues, and associated with poor survival of osteosarcoma patients." (PMID 25890345, 2015). "Furthermore, Nrp2 expression is associated with poor prognosis and reduced overall survival in osteosarcoma patients, and its knockdown in the human osteosarcoma cell line 143B inhibited tumour growth and reduced lung metastasis in mice." (PMID 29720701, 2018). "Captivatingly, upregulation of secreted WNT antagonists decreased NRP2 expression in osteosarcoma cell models suggesting that NRP2 transcription is regulated by WNT pathway." (PMID 34239847, 2021). "Recent studies have reported that osteosarcoma tumours and cell lines overexpress both Nrp1 and Nrp2." (PMID 29720701, 2018). "Further, NRP2 expression is elevated in human osteosarcoma patients (the RNA level) and correlated with hypervascularity, one of the key features of osteosarcoma and a poor prognosis." (PMID 29067024, 2017). "Inhibition of Wnt signaling by overexpression of secreted Wnt antagonists soluble LRP5, Frzb, and WIF1 markedly down-regulated mRNA and protein expression of NRP2 in osteosarcoma cell lines." (PMID 25890345, 2015). "Knockdown of NRP2 expression by short-hairpin (Sh) RNA resulted in reduced tumor growth, metastasis, and blood vessel formation of osteosarcoma." (PMID 25890345, 2015). "Knockdown of NRP2 expression by ShRNA also inhibited the recruitment of HUVEC cells to osteosarcoma cells." (PMID 25890345, 2015). "NRP2 expression is correlated twith increased vascularity and poor prognosis in osteosarcomas and non small cell lung carcinoma (NSCLC)." (PMID 24212788, 2011). "NRP2 was also overexpressed on osteosarcoma cell lines and depletion of NRP2 through downregulation of active Wnt-signaling pathway significantly reduced tumor burden and metastasis by osteosarcoma cell lines." (PMID 29067024, 2017).
viral infection (6 papers, 2019 to 2025). "The importance of the gH/gL pentamer for virus entry was demonstrated by the inhibition of virus infection upon pre-incubation with a soluble neuropilin-2 (NRP-2) entry factor." (PMID 40299764, 2025). "Although out of the scope of this study, these interesting differences suggest that distinct residues are involved in the interaction with NRP1 and NRP2, perhaps implying differential roles during viral infection." (PMID 35931765, 2022). "Yet, anti-Nrp2 mAbs demonstrated a limited effect on virus infection in epithelial cells when compared to trophoblasts." (PMID 31221976, 2019). "Although not essential for hCMV entry into fibroblasts, the combined presence of NRP2 and PDGFRA may increase susceptibility to viral infection." (PMID 40163451, 2025). "The interaction of CD46 with one or several known entry factors (e.g., PDFGRα, Nrp2, CD147, and/or OR14I1) or yet to be identified factors may be required for virus infection by mediating viral endocytosis or viral fusion with the endosomal membrane." (PMID 31221976, 2019).
atherosclerosis (5 papers, 2020 to 2025). A disease characterized by the build-up of fatty material and calcium deposition in the arterial wall resulting in partial or complete occlusion of the arterial lumen. "VEGF-C/NRP2 driven signalling promotes EC migration and survival as well as angiogenesis and lymphangiogenesis —processes associated with vascular neointimal hyperplasia and atherosclerosis." (PMID 32708258, 2020). "Therefore, in the context of atherosclerosis, loss of polySia on macrophage-derived NRP2 may facilitate phagocytosis of lipids and apoptotic cells." (PMID 32708258, 2020). "Previous research has shown that GATA2 can promote the progression of atherosclerosis by upregulating NRP2." (PMID 40963808, 2025). "Mechanistically, GATA2 increases Nrp2 under low sheer stress, which subsequently promotes endothelial cell apoptosis and atherosclerosis via increased PARP1 expression." (PMID 38592275, 2024). "NRP2 is important in angiogenesis, antigen presentation, and phagocytosis, and promotes atherosclerosis." (PMID 36465455, 2022). "Nrp2 has been shown to be upregulated in endothelial cells of mice and HUVECs under low sheer stress, and knockdown of Nrp2 in Apoe-/- mice mitigated the development of atherosclerosis." (PMID 38592275, 2024). "In mouse models of atherosclerosis, depletion of Nrp2 reduces plaque size and lipid content." (PMID 38592275, 2024). "However, given its role in promoting lymphangiogenesis, inhibition of NRP2 may promote plaque growth in advanced atherosclerosis, suggesting a complex role in AMI." (PMID 39417451, 2024).
metastatic tumors (5 papers, 2011 to 2024). "Specifically, during metastatic disease progression, LSMCs reorient along distal tumor-associated lymphatic vessels via a VEGF-C and NRP2-dependent pathway." (PMID 23874750, 2013). "Nrp2 on cancer cells also interacts with α5 integrins on endothelial cells to mediate vascular extravasation and metastasis, and in renal cell carcinoma, is positively correlated with tumor grade and is highest in metastatic tumors." (PMID 38592275, 2024). "Interestingly, even the genes that showed no differential expression in tumors compared to normal samples also showed significantly increased (NRP2 and PLXNC1) or decreased (PLXNB1 and SEMA3F) expression in metastatic tumors (p < 0.0001)." (PMID 32640719, 2020). "Given the role of NRP-2 in tumor cell migration and invasion, targeting NRP-2 offers a potential novel approach to inhibit the growth and survival of cancer cells in patients with metastatic disease." (PMID 22028766, 2011). "In addition, PLXNA3, B2, and B3 had further increased, while NRP2 and PLXNA2 had further decreased expression in metastatic tumors than in primary tumors although none of the differences were significant due to the small number of metastatic tumor samples (n = 7)." (PMID 32640719, 2020). "Furthermore, inhibition of pro-lymphangiogenic factors, such as VEGF-C, VEGF-D, NRP2 and VEGFR3, prior to disease spread can reduce the occurrence of metastatic lesions within SLNs, suggesting that antagonism of this pathway may provide an approach to mitigate metastatic disease." (PMID 23874750, 2013).
non-small cell lung carcinoma (5 papers, 2020 to 2024). A group of at least three distinct histological types of lung cancer, including non-small cell squamous cell carcinoma, adenocarcinoma, and large cell carcinoma. "For instance, it was shown that the KRAS/MAPK/ERK/GLI1 activation could be mediated by either oncogenic KRAS mutation or stimulation of neuropilin 2 (NRP2) by vascular endothelial growth factor (VEGF) in lung adenocarcinoma (LAC) of non-small cell lung cancer (NSCLC)." (PMID 34572373, 2021).
pancreatic ductal adenocarcinoma (5 papers, 2016 to 2025). An infiltrating adenocarcinoma that arises from the epithelial cells of the pancreas. "PMBCs and MBDMs which have been demonstrated to express low basal levels of NRP2 showed markedly upregulated expressions upon activation with conditioned media derived from UNKC-6141 pancreatic ductal adenocarcinoma (PDAC) cells." (PMID 40134439, 2025). "Equally, treatment with the NRP2-specific mAb N2E4 inhibited pancreatic ductal adenocarcinoma cell tumor growth and metastasis by blocking interactions with β1 integrin to inhibit FAK/Erk/HIF1α/VEGF-A165 signaling." (PMID 36970722, 2022).
asthma (4 papers, 2019 to 2024). "Because TLR responses have been implicated in the pathogenesis of type 2‐low asthma, we investigated the role of NRP2 in a murine model of neutrophilic asthma." (PMID 34861108, 2022). "Conditional deletion of NRP2 in myeloid cells exacerbated airway inflammation in a neutrophilic asthma model." (PMID 34861108, 2022). "Gene-based analyses identified NRP2, MRPL44 and SERPINE2 to be associated with various asthma and allergy-related traits." (PMID 30206357, 2019). "Alternatively, because Nrp2 is highly expressed on smooth muscle cells (SMCs) of the colon, and conditional knockout of Nrp2 in SMCs (Nrp2fl/flSM22a-CreERT2) leads to increased contractility, Nrp2 may play a role in SMC contractility during asthma attacks." (PMID 38592275, 2024). "Because Nrp2 is a regulator of TLR-mediated inflammatory responses within the lung, it may also be an effective target for treatment of type-2 low neutrophilic asthma exacerbations." (PMID 38592275, 2024). "Research has shown that the expression of Neurofibroin-2 (Nrp2) is increased in neutrophil asthma mice and is a negative regulatory factor for neutrophil asthma." (PMID 37834319, 2023). "Myeloid‐specific ablation of NRP2 resulted in enhanced airway inflammation in mice with neutrophilic, but not eosinophilic, asthma." (PMID 34861108, 2022). "Indeed, we found that NRP2 was upregulated in lung macrophages in a neutrophilic asthma model, and that lack of NRP2 expression in AM resulted in more severe airway inflammation in mice with neutrophilic, but not eosinophilic, asthma." (PMID 34861108, 2022).
brain tumors (4 papers, 2017 to 2025). "Concerning NRP2, few studies have described its involvement in pediatric brain tumors." (PMID 34277411, 2021). "While SEMA3F suppresses U87 migration via the NRP2/PLXNA1 receptor complex, SEMA3A suppresses brain tumor stem cell proliferation but enhances migration through NRP1/PLXNA1 complex, and PLXNA1-knockdown reduced the growth of GBM in an mice model." (PMID 40533501, 2025). "In contrast, analysis of the closely related Neuropilin 2 (NRP2) gene reveals no upregulation in GBM samples versus normal brain or lower grade brain tumors." (PMID 28938007, 2017).
osteoporosis (4 papers, 2022 to 2025). A condition of reduced bone mass, with decreased cortical thickness and a decrease in the number and size of the trabeculae of cancellous bone (but normal chemical composition), resulting in increased fracture incidence. "The 5 genes (AXL, GAB1, ERBB2, NRP2, and ESR1) along with 13 pharmacological agents represent promising candidates for enhancing the treatment of osteoporosis and sarcopenia." (PMID 40660573, 2025). "The identification of ESR1, NRP2, AXL, ERBB2, and GAB1 as key genes provides novel therapeutic targets and highlights the importance of understanding shared molecular pathways in osteoporosis and sarcopenia." (PMID 40660573, 2025). "In the findings of this study, qRT-PCR validation conducted on patients with sarcopenia and osteoporosis revealed a reduction in the expression of the ESR1 and NRP2 genes in both bone and muscle tissues." (PMID 40660573, 2025). "Furthermore, the generally acidic osteoporotic bone in untreated osteoporosis could support bone metastasis with the secretion of proteins such as COL1A1, COL4A2, NID1, FBLN1, and NRP2." (PMID 35159353, 2022).
ovarian carcinoma (4 papers, 2014 to 2022). A malignant neoplasm originating from the surface ovarian epithelium. "At the individual cancer type level, we found that NRP2 and PLXNA2 were positively, while PLXNB1 and C1 were negatively correlated with ovarian cancer stemness score measured with DNAss, but not with RNAss." (PMID 32640719, 2020).
esophageal squamous cell carcinoma (3 papers, 2017 to 2023). Esophageal squamous cell carcinoma (ESCC) is a type of esophageal carcinoma (EC) that can affect any part of the esophagus, but is usually located in the upper or middle third. "The expression of semaphorin 3F (SEMA3F), a Nrp2 ligand that negatively regulates VEGFR3 activation, is downregulated in esophageal squamous cell carcinoma and is associated with increased VEGF-C and Nrp2 expression." (PMID 38201272, 2023).
invasive breast carcinoma (3 papers, 2009 to 2020). A carcinoma that infiltrates the breast parenchyma. "We demonstrated that miR-146a is an important regulator in invasive breast cancer, regulating NRP2 expression." (PMID 33396906, 2020). "According to the criteria for Nrp2 immunostaining evaluation, Nrp2 protein was positive in 53.1% (60 of 113) of the invasive breast carcinomas." (PMID 19580679, 2009). "Nrp2 expression was observed in 53.1% (60 of 113) of the invasive breast carcinomas." (PMID 19580679, 2009).
lung adenocarcinoma (3 papers, 2021 to 2025). A carcinoma that arises from the lung and is characterized by the presence of malignant glandular epithelial cells. "A study on microRNA-328 (miR-328) secreted by lung adenocarcinoma A549 cells discovered that miR-328, potentially through the downregulation of neuropilin-2 (Nrp-2) expression in A549-derived extracellular vesicles (A549-Exos) in vitro, enhanced OC formation and bone resorption." (PMID 38571500, 2024).